SRSF3 (serine and arginine rich splicing factor 3)
Diseases named in the same sentence as SRSF3 in open-access papers (continued):
Sharing a sentence is not in itself a finding about the gene and the disease.
tumor (continued). "We also verified SRSF3 overexpression in a tissue array (including 50 OSCC tumor and 10 normal oral mucosal samples) by immunohistochemistry." (PMID 26416554, 2015). "In contrast, Srsf3 is tumor-suppressive in mouse liver tissues." (PMID 40568073, 2025). "Interestingly, despite its tumor suppressive function, SRSF3 mRNA is highly expressed in HCC patients." (PMID 40568073, 2025). "Conversely, decreasing the level of miR-6741-3p by a synthetic miR-6741-3p inhibitor and, in turn, increasing the level of SRSF3 in OSCC cells might promote tumor formation in vivo." (PMID 38781195, 2024). "Based on these observations, we hypothesized that the restoration of miR-6741-3p level by a synthetic miR-6741-3p mimic and, in turn, reducing the levels of SRSF3 in OSCC cells might have an anti-tumor effect in vivo." (PMID 38781195, 2024). "Our study suggests a new SRSF3/Ki67/AKR1C2 axis in HNSCC tumor progression." (PMID 36835286, 2023). "Moreover, SFI003 induces the neddylation-dependent degradation of SRSF3 protein and promotes apoptosis, thereby inhibiting cell proliferation, migration, and tumor formation." (PMID 37416784, 2023). "Furthermore, western blotting assays confirmed the remarkably high expression of SRSF3 in NPC tumor tissues compared with control tissues." (PMID 37558679, 2023). "Our study also suggested a new SRSF3/Ki67/AKR1C2 regulatory axis during HNSCC tumor progression." (PMID 36835286, 2023). "Moreover, upregulated SRSF3 expression was remarkably correlated with metastasis and tumor grade of the patient with NPC." (PMID 37558679, 2023). "Additionally, SRSF3 knockdown SRSF3 expression in SW480 significantly inhibits tumor growth in nude mice while it has opposite effects in 786-O, which is consistent to the result of clinical specimen by IHC staining and previous researches." (PMID 35494088, 2022). "Finally, a xenograft tumor experiments were conducted to evaluate the effect of SRSF3 on different types of tumors using knockdown/overexpression level of SRSF3 tumor cells." (PMID 35494088, 2022). "But surprisingly, SRSF3 is negatively correlated with most immune checkpoints of tumors such as BRCA, GBM, LGG, and TGCT, suggesting that SRSF3 may play a negative regulatory role in tumor immunity." (PMID 35494088, 2022). "Moreover, the Clinical Proteomic Tumor Analysis Consortium (CPTAC) data showed that the protein level of SRSF3 was significantly increased in CRC." (PMID 35501301, 2022). "In the present study, double deletion of Igf2 and Srsf3 (DKO mice) prevents hepatic fibrosis and inflammation, and completely prevents tumor formation, and is associated with decreased proliferation, apoptosis and DNA damage, and restored DNA repair enzyme expression." (PMID 35615981, 2022). "In addition, SRSF1 and SRSF3 were found mutually dependent and co-expressed in normal and tumor tissues/cells." (PMID 35463320, 2022). "Moreover, the expression of SRSF3 was higher in more advanced Tumor Node Metastasis (TNM) in ACC, ESCA, KICH, LUAD, and TGCT." (PMID 35494088, 2022). "Besides, we found that ZFAS1 knockdown significantly reduced xenografts sizes and weights compared to control groups, but SRSF3 co-expression reversed tumor progression upon ZFAS1 knockdown." (PMID 35184675, 2022). "This suggests that SRSF3 plays an important role in a variety of tumor immunity." (PMID 35494088, 2022). "SRSF3 is closely related to tumor necrosis factor (TNF)-related ligands and receptors, suggesting that SRSF3 may play an important role in tumor immunity." (PMID 35494088, 2022). "SRSF3-silencing inhibits the proliferation, migration, invasion, and metastasis of tumor cells." (PMID 33072610, 2020). "Targeting SRSF3 in xenograft tumors suppressed tumor progression in vivo." (PMID 32308565, 2020). "SRSF3 knockout results in the exon skipping at exon 7 of transcription factor ETS variant 1 (ETV1) to product ETV1-E7, leading to the enhancement of the proliferation and sphere formation ability of tumor cells." (PMID 33072610, 2020).
tumor (continued). "Aberrant SRSF3 function can be identified in several human diseases, including Alzheimer's disease, systolic heart failure, ocular hypertension, virus infection, and tumor." (PMID 33072610, 2020). "The CRC xenograft experiment in this study also revealed that suppressing SRSF3 could significantly inhibit tumor growth in vivo." (PMID 32308565, 2020). "The downregulation of SRSF3 gene expression might have the ability to regulate tumor initiation, progression, and maintenance." (PMID 29254178, 2017). "Thus, SRSF3‐mediated alterations in miR‐17‐92 processing leading to increased levels of oncogenic miRNAs that promote self‐renewal properties of tumour cells may play a key role in CRC progression." (PMID 37306233, 2023). "Moreover, the IHC results showed that SRSF3 also had higher expression in perivascular tumor cells." (PMID 35198444, 2022). "In addition, SRSF3 was also highly expressed around tumor blood vessels." (PMID 35198444, 2022). "Fourth, SRSF3 directly binds to CCDC50S mRNA, maintaining its stability in the cytoplasm, which is closely related to lower tumor differentiation." (PMID 39034387, 2024). "Taken together, these observations suggest that miR-6741-3p inhibits tumor growth in vivo, in part, by targeting the 3’UTR of SRSF3." (PMID 38781195, 2024). "Taken together, our findings from the in vitro and in vivo assays not only highlight the oncogenic role of SRSF3 during oral carcinogenesis, but also strongly attest to the tumor-suppressive role of miR-6741-3p in OSCC, in part, by targeting SRSF3." (PMID 38781195, 2024). "Our results revealed that miR-6741-3p plays a tumor-suppressive role in OSCC pathogenesis, in part, by directly regulating SRSF3." (PMID 38781195, 2024). "As expected, the SRSFs with CNV amplification displayed significantly higher expression in tumor tissues compared to normal ones (e.g., SRSF1, SRSF2, SRSF3, and SRSF6)." (PMID 38015716, 2023). "As previously observed in vitro, pladienolide B administration in vivo significantly decreased various relevant tumor progression markers and critical oncogenic spliceosome components (VEGFA/EGFR/CDK4/PDGFRA/PDGFRB and SRSF3/PTBP1)." (PMID 35086552, 2022). "However, it is still unclear whether SRSF3 is involved in tumor angiogenesis." (PMID 35198444, 2022). "To further confirm the impact of SRSF3 on CRC growth in vivo, we established a LoVo xenograft tumor model in BALB/C nude mice." (PMID 32308565, 2020). "Spliceosome (RBMX, SRSF3 and U2AF1) was observed as one of the representative events in tumor molecular machinery." (PMID 33261069, 2020). "Specifically, PTEN, a well-known tumor suppressor and lifespan regulator, can be regulated at APA level by SRSF3 in both human and mouse cells." (PMID 30835716, 2019). "The immunoblot analyses confirmed in P3 tumours the up‐regulation of OPN and SERPINA 1, whereas the expression of HDAC2, SRSF3 (spliceosome) and RPS27L (ribosome) was down‐regulated in this type of tumours." (PMID 31560832, 2019). "SRSF3 represses the expression of programmed cell death 4 (PDCD4) protein, which is a tumor suppressor involved in apoptosis, and PDCD4 down-regulation is a potential marker for solid tumor prognoses." (PMID 30279379, 2018). "In in vivo experiments, silencing SRSF3 significantly decreased tumor development and progression, likely by affecting the platelet-derived growth factor receptor beta (PDGFRB) pathway, which plays a critical role in tumor growth and angiogenesis." (PMID 39915450, 2025). "They identified four splicing factors (SRSF3, RBM22, PTBP1, and RBM3) that could accurately distinguish between tumor samples and control samples, as well as different subtypes of tumors from mouse models with gliomas." (PMID 39915450, 2025).
tumor (continued). "Additionally, we observed several cell-type-specific deMuts involved in the spliceosome gene set (GSEA: KEGG pathway), such as SRSF3 and HNRNPC mutants in tumor cells and DDX5 mutants in endothelial cells." (PMID 37433798, 2023). "The TCGA data supported our initial patient cohort data with an increase in SRSF3 expression, downregulation of CDKN1A levels and upregulation of miRNAs of the miR‐17‐92 cluster in tumour samples compared with normal tissue, with the largest increase in miR‐17 and miR‐20a levels." (PMID 37306233, 2023). "SRSF3 and CD276 have significant co-expression (P <0.05), and CD276 (B7-H3), as a possible immune checkpoint molecule, is predicted by researchers to become one of the most promising tumor immunotherapy targets." (PMID 35494088, 2022). "Notably, IR decreases SRSF3 expression and results in an increase in PRMT5-ISO5 levels, which enhances cell radiosensitivity and xenograft tumor regression." (PMID 36499164, 2022). "Notably, DHCR24 expression was positively correlated with SRSF3 and CA199, a tumor marker, in this corpus of CRC tissues." (PMID 35501301, 2022). "The tumor volume in the SRSF3 shRNA group was significantly smaller compared with the control group, indicating that SRSF3 knockdown could significantly suppresse CRC tumor growth in vivo." (PMID 32308565, 2020). "SRSF3 and PDCD4 knockdown could prevent tumor cell apoptosis with decreased Caspase-3 activation and decreased amount of fragmented chromosomal DNA." (PMID 33072610, 2020). "A robust correlation between SF3B1 expression and the most critical oncogenic spliceosome components [SRSF3/RBM22/PTPB1/RBM3] was also found in GBM (CGGA- and Rembrandt-datasets), but not in the non-tumor samples (with the exception of PTBP1; Rembrandt-datasets)." (PMID 35086552, 2022).
infection (6 papers, 2011 to 2024). The state of being infected such as from the introduction of a foreign agent such as serum, vaccine, antigenic substance or organism. "HPV replication is heavily dependent on the expression of some specific splicing factors, such as SRSF2 and SRSF3, at different times during infection." (PMID 31034770, 2019). "SRSF3 and hnRNP M localization were also shown to be impacted by infection from Picornaviridae." (PMID 31034770, 2019). "We quantified DoTT for two marker genes (SRSF3 and DDX5) by qRT-PCR upon infection of primary human fibroblasts with the respective mutant viruses." (PMID 31941886, 2020). "Among the host splicing factors facilitating the regulation of HPV16 and HPV18 RNA splicing, SRSF3 (SRp20) is perhaps the most remarkable host splicing factor, which not only regulates the early-to-late switch of HPV16 and HPV18 productive infection, but also prevents keratinocyte differentiation." (PMID 35563334, 2022). "An addition RNA splicing gene, SRSF3, which is not differential expressed between latency and LTNP groups, showed relatively steady across the infection." (PMID 23451031, 2013).
adenocarcinoma (2 papers, 2016 to 2022). A common cancer characterized by the presence of malignant glandular cells. "In this study, we confirmed that SRSF3 was upregulated in CRC tissues, especially adenocarcinoma tissues, and positively correlated with Ki67." (PMID 35501301, 2022). "Consistent with published data, SRSF3 was highly expressed in 257 (70.6%) CRC tissues, especially in adenocarcinoma tissues (OR = 2.30, P = 0.040), and was positively correlated with Ki67 expression, a proliferation marker (P = 0.040)." (PMID 35501301, 2022). "The DAs of all SFs were not significantly different based on the stage of CR-adenocarcinoma, and the greatest difference between GC and CRC being in SRSF3 was consistently observed regardless of the stage." (PMID 27282379, 2016).
neurological disorders (2 papers, 2021 to 2024). "Srsf3 is also involved in many neurological disorders due to its regulatory role in the alternative splicing of important genes." (PMID 34354569, 2021).
colorectal (1 paper, 2020). "SRSF3 is also involved in colorectal carcinogenesis, however, the specific expression patten and mechanism of SRSF3 in CRC is still unclear." (PMID 32308565, 2020). "Taken together, these results consistently demonstrated a tight association between SRSF3 upregulation and poor CRC prognosis, and suggested that SRSF3 may play a role in colorectal carcinogenesis." (PMID 32308565, 2020).
neurodegenerative disease (1 paper, 2014). A disorder of the central nervous system characterized by gradual and progressive loss of neural tissue and neurologic function. "Because SMA is a neurodegenerative disease, the iPS cells used in this experiment may be one of the better in vitro cellular models for SMA and offer further proof of concept that targeted reduction of cellular SRSF3 would result in an increase in SMN protein in a cell type that is relevant for SMA." (PMID 25506695, 2014).
SRSF3 also shares sentences with these, for which no sentence is quoted: metabolic dysfunction-associated steatohepatitis (3 papers); acute myeloid leukemia (2); amyotrophic lateral sclerosis (2); gastric tumors (2); head and neck squamous cell carcinoma (2); Hepatic steatosis (2); lymphoma (2); non-alcoholic fatty liver disease (2); non-small cell lung carcinoma (2); retinoblastoma (2); acute kidney injury (1); aneurysmal bone cyst (1); asthma (1); bipolar disorder (1); bone cancer (1); chronic lymphocytic leukaemia (1); dyskeratosis congenita (1); enterovirus infections (1); Fanconi anemia (1); heart failure (1); hematological malignancies (1); Hepatitis (1); hepatocellular adenoma (1); Herpes simplex infection (1); liposarcoma (1); lung adenoma (1); metastatic tumors (1); muscular dystrophy (1); nasopharyngeal carcinoma (1); neuroblastoma (1).
A further 8 diseases each share a sentence with SRSF3 in 1 paper.